TLR4 (toll like receptor 4)
Diseases named in the same sentence as TLR4 in open-access papers (continued):
Sharing a sentence is not in itself a finding about the gene and the disease.
bone cancer (continued). "The TLR4 mRNA levels in the L4~6 lumbar spinal cord from mismatch siRNA- and vehicle- treated bone cancer pain rats were higher (62% ± 8 in IBCP group; 70% ± 6 in WBCP group, n = 4) relative to that of normal rats." (PMID 20089147, 2010). "This study demonstrates a critical role in CNS innate immunity of the microglial Toll-like receptor 4 (TLR4) in the induction and maintenance of behavioral hypersensitivity in a rat model of bone cancer pain with the technique of RNA interference (RNAi)." (PMID 20089147, 2010). "This is further evidenced by the present study's finding that functional knockdown of the TLR4 gene by RNAi significantly inhibited bone cancer-induced behavioral hypersensitivity." (PMID 20089147, 2010). "Meanwhile, a report revealed that TLR4-deficient mice have reduced bone destruction following mixed anaerobic infection, which suggests that TLR4 is involved in bone cancer-induced pain perception." (PMID 20089147, 2010). "The relative levels of spinal TLR4 mRNA were significantly higher (n = 4, ANOVA1w, P < 0.01, post hoc Dunnett testing) in bone cancer pain rats than in sham rats, on the sixth day after inoculation." (PMID 20089147, 2010). "The data presented herein demonstrate a key role for microglial TLR4 in the induction and maintenance of behavioral hypersensitivity in rodent models of bone cancer pain." (PMID 20089147, 2010). "Consistent with the behavioral test, the real-time RT-PCR study and western-blot analysis demonstrated that TLR4 significantly suppresses spinal TLR4 mRNA and protein expression during bone cancer pain." (PMID 20089147, 2010). "Gene knockdown of TLR4 prevents and reverses bone cancer pain in female rats." (PMID 41511304, 2025). "Interestingly, a recent study identified this same target, TLR4, as a mechanism of chronic morphine-induced pain in a murine model of bone cancer pain, potentially limiting opioids as a treatment for CIBP." (PMID 37834455, 2023). "TLR4 ablation or inhibition by siRNA or antagonist attenuates arthritic pain and bone cancer pain." (PMID 36277489, 2022). "All these suggested that TLR4 signal pathway may involve bone cancer pain and that attenuation of TLR4 may probably be a new treatment of bone cancer pain." (PMID 26556957, 2015). "Our findings suggest that the lentivirus-mediated siRNA against TLR4 may be used for gene therapy of bone cancer pain in an experimental setting." (PMID 26556957, 2015). "If this is successful, the downregulation of TLR4 expression by inducible lentivirus LvOn-siTLR4 may be used to treat bone cancer pain in clinic." (PMID 26556957, 2015). "This is also observed in rats with bone cancer pain were treated intrathecally with TLR4 siRNA." (PMID 24499354, 2014). "In the present report, we show that intrathecal TLR4 siRNA could prevent bone cancer-induced tactile allodynia and spontaneous pain at an early stage of tumor growth." (PMID 20089147, 2010). "Thus, it is very important that TLR4 provides a mechanistic link between microglial activation, innate immunity, and the initiation of behavioral hypersensitivity in the rat model of bone cancer pain." (PMID 20089147, 2010). "This suggests that expression of TLR4 mRNA was up-regulated by the induction of bone cancer." (PMID 20089147, 2010). "In the present study, we showed that downregulation of TLR4 by intrathecal injection of inducible lentivirus LvOn-siTLR4 could prevent bone cancer-induced tactile allodynia and that TLR4 expression could be controlled by doxycycline in regulation of the lentivirus." (PMID 26556957, 2015). "The results showed that LvOn-siTLR4 intrathecal injection along with oral administration of doxycycline attenuated allodynia of rats, which suggested that the lentivirus LvOn-siTLR4 could suppress nociception in the bone cancer models through decreasing the expression of TLR4." (PMID 26556957, 2015). "It is hypothesized that TLR4 could serve as the main mediator in induction of bone cancer pain." (PMID 21722369, 2011).
bone cancer (continued). "The ability of TLR4 to activate a pathway leading to central sensitization and behavioral hypersensitivity could provide an opportunity for regulating glial activation, and thus, alleviating chronic pain, such as bone cancer pain." (PMID 20089147, 2010). "TLR4 might be the main mediator in the induction of bone cancer pain." (PMID 20089147, 2010). "Blocking the TLR4 signaling pathway could potentiate analgesic effects in bone cancer pain." (PMID 20089147, 2010). "Thus, we speculated that the immune response mediated by the TLR4 signaling pathway might be involved in the induction and maintenance of bone cancer pain." (PMID 20089147, 2010). "Thus, blocking the TLR4 signaling pathway might be a useful way of treating bone cancer pain." (PMID 26556957, 2015). "A recent study from our laboratory demonstrated a critical role in CNS innate immunity for the microglial Toll-like receptor 4 (TLR4) in induction and maintenance of behavioral hypersensitivity in a rat model of bone cancer pain." (PMID 21722369, 2011). "However, at the late stage, intrathecal TLR4 siRNA can only attenuate, but not completely block, well-established bone cancer pain." (PMID 20089147, 2010). "Third, we tested whether TLR4 blockade by intrathecal injection of siRNA could reverse well-established bone cancer pain, and not simply prevent its initial development, because reversal is the more clinically relevant endpoint." (PMID 20089147, 2010). "However, the ambulatory score was still higher than normal rats (P < 0.05), which indicated that intrathecal injection of TLR4 siRNA439 could alleviate, but not reverse, well-established bone cancer pain." (PMID 20089147, 2010).
cholesteatoma (12 papers, 2014 to 2023). A pathologic process characterized by the proliferation of keratinizing squamous epithelium resulting in the accumulation of keratin and cells in the middle ear and/or mastoid. "Aggressiveness of cholesteatoma is strongly associated with the presence of bacteria and bacterial LPS as the common agonist of TLR4." (PMID 31947538, 2020). "Since bacterial infections are strongly associated to cholesteatoma growth and progression, we found TLR4 to be highly upregulated in ME-CSCs." (PMID 31947538, 2020). "The number of TLR4-positive cells increased with an increased degree of cholesteatoma invasion, bone destruction, and hearing loss." (PMID 26639190, 2015). "Importantly, TLR4-deficiency in mice was already shown to be protective against cholesteatoma-driven hearing loss and bone destruction by reduction of local expression of pro-inflammatory cytokines and osteoclast formation." (PMID 31947538, 2020). "Furthermore the stem cells derived from the cholesteatoma showed a higher expression of the Toll-like receptor 4 (TLR4) and a higher susceptibility to inflammatory stimulus in-vitro in comparison to stem cells derived from healthy auditory canal skin." (PMID 29670222, 2018). "Next, we assessed the expression of TLRs and downstream cytokines to evaluate whether TLR4 is associated with acquired cholesteatoma-induced bone resorption." (PMID 26639190, 2015). "Therefore, TLR4 is required for acquired cholesteatoma-induced bone destruction, but the underlying mechanism still remains unclear." (PMID 26639190, 2015). "Of course, LPS helps to generate the destructive proinflammatory environment in cholesteatoma tissue by stimulating the TLR4 in various cell types present in cholesteatoma tissue." (PMID 33627146, 2021). "TLR4 signalling can also be induced by the DAMPs abundant in cholesteatoma tissue e.g. high-mobility group box 1 proteins (HMGB1), Tenascin, fibronectin, S100A8, S100A9 and also HSP60 and HSP70." (PMID 33627146, 2021). "We propose that cholesteatoma recurrence is based on TLR4 signalling imprinted in the cholesteatoma cells." (PMID 33627146, 2021). "Taken our experimental results together, the high recurrence upon infection of cholesteatoma might be supported by an enhanced proliferation of ME-CFs and the increased epidermal differentiation of ME-CSCs upon paracrine stimulation of ME-CFs both caused upon TLR4 stimulation." (PMID 33627146, 2021). "For cholesteatoma tissue, the ME-CSCs and ME-CFs showed a similar distribution of TLR4 expression between 1 and 0.1% relative to GAPDH." (PMID 33627146, 2021). "In summary, we determined that ME-CSCs mediate the inflammatory environment of cholesteatoma via TLR4-mediated NF-κB-signaling, suggesting a distinct role of ME-CSCs as drivers of cholesteatoma progression and TLR4 on ME-CSCs as a therapeutic target." (PMID 31947538, 2020). "ME-CSCs and ACSCs were exposed to the TLR4 agonist LPS from S. enterica in order to model the cholesteatoma microenvironment." (PMID 31947538, 2020). "In summary, we determined that ME-CSCs regulate the inflammatory environment of cholesteatoma via TLR4-mediated NF-κB-signaling, suggesting a distinct role of ME-CSCs as drivers of cholesteatoma progression in an inflammation-dependent manner." (PMID 31947538, 2020). "To determine a potential contribution of ME-CSCs to the pro-inflammatory environment of cholesteatoma, we investigated expression levels of TLR4 in ME-CSCs and ACSCs." (PMID 31947538, 2020). "The occurrence of participants of the innate immunity, TLR2 and TLR4, were analysed in order to compare healthy middle ear mucosa to cholesteatoma." (PMID 32915926, 2020). "In 2015, Si and colleagues extended these findings by demonstrating TLR4 as a major driver of cholesteatoma pathogenesis in terms of promoting both inflammation and bone destruction." (PMID 31947538, 2020).
cholesteatoma (continued). "In the present study, we demonstrate that stem cells residing in cholesteatoma, a severe expanding lesion in the middle ear, mediating its inflammatory environment in a TLR4-NF-κB-dependent manner." (PMID 31947538, 2020). "Cholesteatoma tissue is highly inflamed and possesses inflammatory characteristics such as enhanced TLR4 expression." (PMID 29670222, 2018). "Since TLR4 is a crucial mediator of inflammatory signalling, we analysed cholesteatoma tissue for TLR4-expression." (PMID 29670222, 2018). "We have reported that TLR2, TLR3, and TLR4 are expressed in epithelial cells, including human acquired cholesteatoma and cancer cells." (PMID 25385222, 2015). "Among all TLRs that we tested,TLR4 was the most abundantly expressed in acquired cholesteatoma, followed by TLR2." (PMID 26639190, 2015). "TLR4 expression in human acquired cholesteatoma correlated with disease severity; the number of TLR4-positive cells increased with an increased degree of cholesteatoma, invasion, bone destruction, and hearing loss." (PMID 26639190, 2015). "We used WT,TLR2−/−, and TLR4−/− mice to establish experimental models of cholesteatoma and evaluated the clinical features of these mice." (PMID 26639190, 2015). "We correlated TLR4-positive cell counts with the clinical characteristics of acquired cholesteatoma patients." (PMID 26639190, 2015). "Interestingly, the TLR4 expression tended to be lower in fibroblasts and higher in stem cells derived from cholesteatoma compared to the same cell type from auditory canal skin." (PMID 33627146, 2021). "Treatment of the operation site with a TLR4 antagonist might reduce the chance of cholesteatoma recurrence." (PMID 33627146, 2021). "Under standard culture conditions, we detected a tissue-independent higher expression of IL-1β and IL-8 in stem cells, an upregulation of KGF and IGF-2 in both cell types derived from cholesteatoma and higher expression of TLR4 in stem cells derived from cholesteatoma tissue." (PMID 33627146, 2021). "Previous studies have shown dysregulation of TLR2 and TLR4 within the cholesteatoma matrix itself." (PMID 32915926, 2020). "In the presented study, we utilized our established human in vitro cholesteatoma stem cell model for treatments with lipopolysaccharides (LPS), tumor necrosis factor α (TNFα), and the TLR4-antagonist LPS from R. sphaeroides (LPS-RS) followed by qPCR, western blot, and immunocytochemistry." (PMID 31947538, 2020). "In addition, an enhanced expression of the Toll-like receptor 4 (TLR4) was observed in cholesteatoma tissue compared to external auditory canal skin tissue." (PMID 31947538, 2020). "Besides increased TLR4-expression, different cytokines are also known to be expressed in cholesteatoma tissue." (PMID 29670222, 2018). "Therefore, we believed that TREM-2 amplified the inflammatory response in experimentally acquired cholesteatoma via the TLR4 signaling pathway." (PMID 27934908, 2016). "We found that the number of TLR4-positive cells was much higher in human acquired cholesteatoma." (PMID 26639190, 2015). "Furthermore, we established experimental cholesteatoma models to verify the manner in which TLR4 promotes acquired cholesteatoma-induced bone destruction." (PMID 26639190, 2015). "Importantly, we found the TLR4 signalling reacts much more sensitive upon LPS stimulation in ME-CSCs and ME-CFs compared to ACSCs and ACFs resulting in the pathological inflammatory state in cholesteatoma tissue." (PMID 33627146, 2021). "Therefore, we speculated that TREM-2 is up-regulated and is responsible for bone destruction in human acquired cholesteatoma via the TLR4 pathway, based on the results of this study." (PMID 27934908, 2016). "Therefore, TREM-2 might enhance acquired cholesteatoma-induced bone destruction by amplifying the inflammatory response via TLR4 signaling pathways and promoting MMP secretion and osteoclast activation." (PMID 27934908, 2016).
cholesteatoma (continued). "Moreover, TLR2 deficiency did not relieve disease severity, inflammatory responses, or osteoclast formation.Therefore, the pathogenesis of acquired cholesteatoma may be dependent on TLR4 instead of TLR2." (PMID 26639190, 2015). "Therefore, TLR4 may promote cholesteatoma-induced bone destruction and deafness by enhancing inflammatory responses and osteoclastogenesis." (PMID 26639190, 2015). "A comparison of TLR4 expression in normal canal skin, COM, and cholesteatoma showed that TLR4 mRNA and protein levels were increased in mucosa and granulation tissue of COM and cholesteatoma patients compared with those in normal external auditory canal skin." (PMID 34360632, 2021). "We assume that pathogenesis as well as recurrence of cholesteatoma tissue upon TLR4 signalling can also be initiated by a non-infectious inflammatory response following tissue injury abundant in cholesteatoma." (PMID 33627146, 2021). "Functional inactivation of TLR4 via the TLR4-antagonist LPS-RS blocked pro-inflammatory signaling in ME-CSCs, thus providing a direct clinical perspective for pharmaceutical cholesteatoma treatment that is not present today." (PMID 31947538, 2020). "Using this method, we aimed to investigate whether the middle ear mucosa in ears with cholesteatoma has altered gene expression in relation to its control tissue by the examination of TLR2, TLR4 and c-MYC." (PMID 32915926, 2020). "However, the expression and function of TLRs in cholesteatoma remain unclear.We observed inflammatory cell infiltration of the matrix and prematrix of human acquired cholesteatoma, as well as dramatically increased expression of TLR4 and the pro-inflammatory cytokines TNF-α and IL-1β." (PMID 26639190, 2015). "Microarray analysis showed significant upregulation for NOD2, not for NOD1, TLR2, or TLR4 in cholesteatoma." (PMID 25922834, 2015). "From immunohistochemistry studies of biopsies from the normal ear canal and acquired cholesteatoma (an abnormal growth of keratinized squamous epithelium), it appears that expression of TLR2, TLR3 and TLR4 is detected and regulated as a function of cholesteatoma." (PMID 25161655, 2014). "We could not observe any clear dysregulation of TLR2 or TLR4 mRNA in the mucosa from patients with cholesteatoma." (PMID 32915926, 2020). "A down-regulation of TLR4 was seen in middle ear mucosa from a group of patients with CMED, including cholesteatoma and an up-regelation of TLR2 and 4 in immunohistochemical analysis in tissue samples from five cholesteatoma patients, in comparison to normal mucosa, was detected respectively." (PMID 32915926, 2020). "Interestingly, LPS is by far not the only way to activate TLR4 signalling in cholesteatoma tissue." (PMID 33627146, 2021). "Studies have shown that TLR4 is not expressed in normal middle ear samples, but is readily detected in COM and cholesteatoma." (PMID 34360632, 2021). "It has been shown that TLR4 is expressed in AOM, OME, COM with cholesteatoma, and COM without cholesteatoma, and is closely related to the etiology of otitis media." (PMID 34360632, 2021). "Among all the TLRs that we tested, TLR4 but not TLR2 was up-regulated and related to the disease severity of human acquired cholesteatoma.TLRs recognize numerous structurally defined but not necessarily structurally related ligands." (PMID 26639190, 2015).
dementia (12 papers, 2018 to 2025). Loss of intellectual abilities interfering with an individual's social and occupational functions. "Thus, TLR4 activation by AGE or HMGB1 can increase the risk of dementia trough promoting brain-insulin resistance." (PMID 37373216, 2023). "Moreover, TLR4-mediated inflammatory responses may lead to synaptic dysfunction and neuronal loss, which are key features of dementia." (PMID 40872491, 2025). "TLR4 activation plays an important role in the progression of diseases such as neuroinflammation, AD, and dementia." (PMID 40872491, 2025). "It will be interesting to examine if A1B suppresses chronic inflammation that occurs in neurodegenerative diseases including AD and related dementias by modulating the cellular fate of TLR4." (PMID 36982689, 2023). "Conversely, the inhibition of TLR4 expression may slow the progression of neuroinflammation, AD, and related dementias." (PMID 40872491, 2025). "Moreover, a significant positive correlation between SIRT1 levels and dementia was found whereby dementia risk increases by a factor of 1.16 due to an increase in the SIRT1 level and a factor of 24.23 due to a decrease in the TLR4 level." (PMID 30555513, 2018). "In the future perspectives, effect of DHQ on LPS and amyloid beta induced activation of NF-kappa B via toll like receptor-4 activation in the microglial cells can be explored as NF-kappa B is one of the potential targets for neuroinflammation and related complications like dementia." (PMID 35243333, 2022). "In addition, inhibiting the expression of TLR4, a receptor on microglia, reduces microglial activation and the release of inflammatory cytokines, including IL-6, TNF-α, and IL-1β, alleviating the chronic neuroinflammation associated with AD and other dementias." (PMID 40872491, 2025). "Supplementation with probiotics therefore has the potential to prevent the disease and delay dementia, as it can modulate the gut-brain axis by reducing NLRP3, TLR4 and MYD88 inflammatory pathways triggered by the overgrowth of pathogenic bacteria." (PMID 40376196, 2025). "Moreover, small molecule antagonists of TLR4 have recently been developed and protect against neuro-toxicity using in vitro models of ALS and LPS-induced neuro-inflammation, suggesting that an investigation of the potential of these drugs in dementia models is warranted." (PMID 30210290, 2018).